MYCN (MYCN proto-oncogene, bHLH transcription factor)
Diseases named in the same sentence as MYCN in open-access papers (continued):
Sharing a sentence is not in itself a finding about the gene and the disease.
neuroblastoma (continued). "Conversely, the most aggressive neuroblastoma presenting MYCN amplification also displayed down-regulation of Cdc42 expression through the control of N-myc, indicating that Rho GTPases overexpression is not always correlated with poor prognosis." (PMID 32664294, 2020). "Specifically, MDM2 was found to upregulate MYCN RNA levels and MYCN translation in NB1691 and SK-N-SH neuroblastoma cells and in RB176 and Y79 retinoblastoma cells, effects attributed to MYCN RNA stabilization and ribosomal loading in the neuroblastoma setting." (PMID 33425720, 2020). "As an example of clinical application, a patient (No. 060) was diagnosed with stage 4, MYCN amplified neuroblastoma." (PMID 31747416, 2019). "By RT-PCR analysis, we confirmed that lncNB1 was expressed at considerably higher levels in five MYCN-amplified, compared with three MYCN-non-amplified neuroblastoma cell lines." (PMID 31690716, 2019). "We aimed to knock down PRMT1 expression in a neuroblastoma cell line that is not MYCN-amplified or overexpressed to study the effects of low PRMT1 levels in these cells." (PMID 30741995, 2019). "In neuroblastoma cells, PLK1 enhances stability of MYCN by antagonizing FBW7-mediated degradation." (PMID 31455158, 2019). "Notably, it was previously shown that transcription of MYCN in MYCN amplified neuroblastoma cells relies on BRD4 expression and that BRD4 inhibition by BET-bromodomain inhibitors decreases MYCN expression." (PMID 31414211, 2019). "PTH1R mRNA was found significantly higher in patients with age at diagnosis < 18 months and in MYCN nonamplified neuroblastomas, although this was not an independent predictor of outcome in multivariate analyses." (PMID 31293052, 2019). "CFZ was effective to both MYCN-amplified and non-MYCN-amplified neuroblastoma cells with slight differences in IC50 values in our experimental condition." (PMID 30911132, 2019). "Chromosome band 11q23 deletion predicts poor prognosis only in bone marrow metastatic neuroblastoma patients without MYCN amplification." (PMID 31685009, 2019). "We therefore conclude that treatment with low cytotoxic doses of quarfloxin and CX-5461 does not significantly inhibit ribosomal biogenesis in MYCN-amplified neuroblastoma cell lines." (PMID 30542116, 2019). "Considering that the strongest DHA induction by MYCN depletion occurred in MYCN-amplified cells, we speculated that the endogenous DHA content are different in neuroblastoma cell lines with different MYCN genomic statuses." (PMID 31856871, 2019). "Inhibition of α5β1 integrin using a blocking antibody has been shown to increase cell motility in single-copy MYCN neuroblastoma cells, but not in MYCN-amplified neuroblastoma cells." (PMID 30836897, 2019). "In neuroblastoma tumors without MYCN amplification, TAMs were shown to activate the STAT3 pathway in an IL-6 independent manner, leading to enhanced tumorigenesis." (PMID 31828566, 2019). "Contrarily, our data indicate that PTH1R expression is higher in the least malignant, MYCN nonamplified neuroblastic tumors, and its knockdown promoted increased cell invasion and migration in neuroblastoma cell lines." (PMID 31293052, 2019). "We also compared H3K27ac signals at regions bound by LMO1 in Kelly cells across a panel of neuroblastoma cell lines without MYCN amplification that expressed different levels of LMO1." (PMID 31819055, 2019). "In neuroblastoma models, I-BET 762 triggered apoptosis via BET inhibition of both MYCN and Bcl-2." (PMID 30906568, 2019). "On the other hand, FAK knockdown has been found to decrease cell motility in MYCN-amplified neuroblastoma cells, but not in single-copy MYCN neuroblastoma cells." (PMID 30836897, 2019). "Univariate analysis showed that age of diagnosis (>520 day), race of American Indian or Alaska Native, stage 4 in International Neuroblastoma Staging System (INSS), MYCN status, DNA ploidy, and high mitosis-karyorrhexis index were associated with overall survival (OS)." (PMID 31338261, 2019).
neuroblastoma (continued). "CCR2 (expressed by NKT cells) and CCL2 (expressed by a subset of MYCN non-amplified neuroblastoma cells) mediated homing of NKT cells to neuroblastoma was shown in subset of neuroblastoma patients." (PMID 31620124, 2019). "While microarrays have identified a number of protein-coding genes considerably differentially expressed between MYCN-amplified and non-amplified human neuroblastoma cell lines, the technology does not cover the majority of lncRNAs." (PMID 31690716, 2019). "Conversely, previous studies revealed that PRMT1 is positively correlated with MYCN in a large Kocak dataset with 476 patients with non-MYCN classified neuroblastoma." (PMID 30741995, 2019). "We first evaluated the mRNA expression levels of MTHFD2, PAICS, and MYCN in 21 tissue samples from neuroblastoma patients (MNA: n = 9; non-MNA: n = 12)." (PMID 31624245, 2019). "We performed RNA sequencing experiments with RNA from MYCN-amplified and non-amplified human neuroblastoma cell lines." (PMID 31690716, 2019). "Together, these data demonstrate that decreased levels of CTNNA2 are worse and associated with disease relapse and mortality in neuroblastoma patients, especially in those with neuroblastoma lacking MYCN-amplification." (PMID 31489113, 2019). "Nutlin-3 and MI-63, both MDM2 inhibitors, have more effectively suppressed proliferation of MYCN-amplified neuroblastoma cells compared to cells lacking MYCN amplifications." (PMID 29416773, 2018). "In fact, BMI1 expression, a gene, whose suppression resulted in significantly greater inhibition of cell growth, correlated with MYCN levels in MYCN-amplified neuroblastoma cells, and with MYC levels in the MYCN-nonamplified group." (PMID 30134948, 2018). "Remarkably, the effector of all these circuits is the MYC protein, which seems to be the counterpart of MYCN in patients with MYCN-nonamplified neuroblastomas." (PMID 30134948, 2018). "In neuroblastoma (NB), the most powerful prognostic marker, the MYCN amplification (MNA), occasionally shows intratumoural heterogeneity (ITH), i.e. coexistence of MYCN-amplified and non-MYCN-amplified tumour cell clones, called heterogeneous MNA (hetMNA)." (PMID 29755120, 2018). "High ESC m(i)RNA expression signature scores were significantly correlated with poor neuroblastoma patient outcome specifically in the subgroup of MYCN amplified tumors and stage 4 nonamplified tumors." (PMID 30504901, 2018). "In addition, the function of MYCN/MAX and C-Myc/MAX heterodimers as global transcriptional amplifiers regulated by super-enhancer elements likely also plays a major role in neuroblastoma development." (PMID 29755654, 2018). "For this purpose, we first utilized a panel of neuroblastoma cell lines with or without MYCN-amplification." (PMID 29968736, 2018). "Among these morphologic indicators, there is a reproducible relationship between MYCN amplification and increased MKI classes: Our recent study confirmed that 68% of High-MKI, 15% of Intermediate-MKI, and only 3% of Low-MKI neuroblastomas had MYCN oncogene amplification." (PMID 29464082, 2018). "We thus examined PD-L1 expression in both mouse and human cell lines, comparing mouse WT (Neuro2a) to aggressive (AgN2a) neuroblastoma and human non-MYCN-amplified SK-N-SH to MYCN-amplified IMR-32 cell lines." (PMID 29377881, 2018). "Not unexpectedly, a subset of high-stage neuroblastoma tumors without MYCN amplification also have elevated ESC signature scores, in keeping with high MYC activity in these cells." (PMID 30504901, 2018). "Although MYCN amplification has been identified as a marker of poor prognosis for neuroblastoma, no therapeutic drug has been developed to target MYCN directly." (PMID 29880876, 2018). "However, in human neuroblastoma TERT rearrangements rarely, if ever, co-occur with MYCN or ATRX alterations." (PMID 29492199, 2018).
neuroblastoma (continued). "The survival difference for tumors with different scores is most striking for high-stage neuroblastoma tumors without MYCN amplification, while all tumors with MYCN amplification have higher ESC miRNA signature scores compared to non-amplified tumors." (PMID 30504901, 2018). "Functionally, miR-193b induces a G1 cell cycle arrest and cell death in neuroblastoma cell lines by reducing the expression of MYCN, Cyclin D1 and MCL-1, three important oncogenes in neuroblastoma of which inhibition has shown promising results in preclinical testing." (PMID 29719597, 2018). "Whole-genome sequencing of 108 neuroblastoma cases revealed TERT rearrangements in 23% of stage 3 and 4 cases regardless of MYCN amplification or ATRX mutations and also confirmed this to be an independent prognostic factor." (PMID 30326621, 2018). "Furthermore, several studies have shown that aberrant ALK signaling in neuroblastoma cells regulates MYC and MYCN transcriptional initiation and protein stability." (PMID 29507657, 2018). "Recently, a mathematical model was used to demonstrate that the network regulating stress signaling by the c-Jun N-terminal kinase pathway played a crucial role in survival of patients with neuroblastoma irrespective of their MYCN amplification status." (PMID 30134948, 2018). "Utilizing a MYCN-amplified neuroblastoma xenograft tumor model, we could show that MYCMI-6 treatment significantly reduced MYCN:MAX interaction in tumor tissue, suggesting that MYCMI-6 reached and was active against its target in vivo." (PMID 29968736, 2018). "Taken together, we propose a model that posits that, in MYCN-amplified neuroblastoma, high levels of MYCN upregulate the master regulator TFAP4, which in turn activates downstream oncogenic signaling pathways to promote cell cycle progression and inhibit neuroblastoma differentiation." (PMID 29880876, 2018). "RNA-Seq expression levels (fragments per kilobase of exon per million fragments mapped (FPKM)) showed high levels of MYC in human Group 3 MB lines D283, sD425, and MB002 and high levels of MYCN in GTML2 cells and in a human neuroblastoma cell line, Kelly, that was also included in the analysis." (PMID 29511348, 2018). "We show that cellular delivery of BLF1 selectively induces apoptosis in neuroblastoma cells that display MYCN amplification but has little effect on non-transformed cells." (PMID 29954071, 2018). "Despite its well-defined negative impact on clinical outcome, the mechanisms distinguishing the clinical behavior of MYCN amplified and non-amplified neuroblastoma remain poorly defined." (PMID 29755654, 2018). "TMOD2 is part of a 160 gene signatures predicting neuroblastoma outcome and of a 55 gene signature predicting neuroblastoma outcome in metastatic neuroblastoma lacking MYCN amplification." (PMID 29930753, 2018). "Highly aggressive MYC-driven neuroblastoma is defined by increased c-MYC and/or MYCN expression." (PMID 30237861, 2018). "However, our previous work demonstrated that Wnt3a/Rspo2 treatment of some neuroblastoma cell lines can, paradoxically, decrease c-MYC and MYCN proteins." (PMID 29505958, 2018). "It is of interest to note that in this series of High-MKI neuroblastomas, there were a total of 22 tumors with prominent nucleolar formation which did not express excess amount of MYCN or MYC protein." (PMID 29464082, 2018). "The mechanisms through which MYCN blocks RA-mediated neuronal differentiation are highly relevant to MYCN-amplified neuroblastoma patients, who generally do not respond well to retinoid treatment." (PMID 28187790, 2017).
neuroblastoma (continued). "Herein, we show that integrin αvβ3 was expressed on 68% of microvessels in MYCN-amplified stage 3 neuroblastomas, but only on 34% (means) in MYCN-non-amplified tumors (p < 0.001; n = 54)." (PMID 28881723, 2017). "We validated this pathway on the additional sampling of 5 MYCN-amplified and 36 non-amplified neuroblastoma samples, experimentally profiled here using an alternative microarray platform." (PMID 29137381, 2017). "Soon after, amplifications of MYCN and MYCL were discovered in cell lines and tumors of neuroblastoma and small cell lung cancer, respectively, with small cell lung cancer being the first cancer found to have amplifications of all three transforming MYC family members." (PMID 28587062, 2017). "Our examination of GAS5 in neuroblastoma has revealed robust expression in both MYCN-amplified and non-amplified cell lines." (PMID 28035057, 2017). "We selected 15 neuroblastoma cell lines previously reported to harbor MYCN and/or ALK amplifications, gains or the normal diploid chromosomal complements in the regions of MYCN and ALK as a panel in which to validate detection of gene amplification or gain by ddPCR." (PMID 29156716, 2017). "MYCN copy numbers determined using ddPCR in gDNA confirmed the gain in LAN-6 and normal diploid status in the SK-N-AS, SH-EP, SK-N-FI, NBL-S and CLB-GA neuroblastoma cell lines, which are reported in the literature." (PMID 29156716, 2017). "In order to determine the function of GAS5 expression in human neuroblastoma, both MYCN-amplified (IMR-32) and non-amplified (SK-N-AS) cell lines were transfected with two separate GAS5 siRNAs." (PMID 28035057, 2017). "For example, NCAM1 (also known as CD56) is a main carrier for the neural crest stem cell marker and its reduced expression is correlated with unfavorable prognosis in neuroblastoma with distant metastases, regardless of the MYCN amplification status." (PMID 28984200, 2017). "To analyze the effect of MG-2477 on the survival of neuroblastoma cells, we chose a set of cell lines that are derived from different tumor stages and vary in PKB expression and PKB activity (phosphoPKB/PKB ratio from 1.2 to 8.6) and MYCN status." (PMID 28415610, 2017). "In our current series of stage 3 neuroblastomas the expression of integrin αvβ3 on tumor microvessels was predictive of survival in a univariate analysis, but not after adjusting for MYCN and Shimada classification." (PMID 28881723, 2017). "Ruxolitinib was also effective at blocking the macrophage-dependent STAT3 phosphorylation and MYC up-regulation in MYCN non-amplified human neuroblastoma cells." (PMID 29207662, 2017). "Exogenous expression of MYCN confers MYCN non-amplified neuroblastoma cells with an increased proliferative rate and tumorigenic capacity, mediated by enhanced autocrine growth-factor activity." (PMID 28358317, 2017). "In our study, which included 30 newborns (aged 0–1 months) with Neuroblastoma, we found that MYCN was not amplified in 29/29 (100%) of cases." (PMID 28056863, 2017). "In contrast, glutamine deprivation did not affect growth or survival of non-MYC amplified NCI-H345 SCLC cells and non-MYCN amplified SH-SY5Y neuroblastoma cells within the time frame tested." (PMID 28430666, 2017). "The effects of GSK461364 on G2/M arrest and apoptosis in neuroblastoma cells did not appear to be influenced by the cellular MYCN background (single copy vs. amplified)." (PMID 28036269, 2017).
neuroblastoma (continued). "Messenger RNA of cell lines derived from the spontaneously-arising neuroblastoma tumors confirmed reduced Pten mRNA in MYCN PTEN+/− cells compared to MYCN PTEN +/+ cells, without difference in Mycn mRNA levels." (PMID 28881723, 2017). "As we are primarily focused on evaluating TIN and its role in HR neuroblastoma patients, we used the mean gene expressions of stage 1 MYCN nonamplified localized tumors as reference values." (PMID 28941026, 2017). "In summary, our findings uncover a previously unidentified model in the control of EMT, suggesting that MYCN/LSD1 inhibition de-represses NDRG1 expression, thereby inducing an NDRG1-dependent inhibitory effect on cell migration and invasiveness of neuroblastoma cells." (PMID 27894074, 2017). "To study TAM action in neuroblastomas, we used a novel murine model of spontaneous neuroblastoma lacking MYCN amplification, and observed recruitment and polarization of TAMs, which in turn enhanced neuroblastoma proliferation and growth." (PMID 29207662, 2017). "Our analysis of GAS5 in neuroblastoma indicates it is expressed in both MYCN-amplified and non-amplified cell lines." (PMID 28035057, 2017). "While MYCN amplification and unbalanced 11q aberration have emerged as the dominant factors in risk assignment, poorly differentiated or undifferentiated ganglioneuroblastoma, and NB without these genetic alterations can also show poor prognosis." (PMID 29163537, 2017). "In addition, MYCN has been shown to upregulate the transcription of RPS and RPL genes and translation initiation and elongation factors in human neuroblastoma cell lines." (PMID 28425916, 2017). "Our results in neuroblastoma cell lines with and without MYCN amplifications collectively highlight the significance of HDAC11 expression for cellular viability, particularly in the presence of MYCN amplification." (PMID 28252645, 2017). "Similarly, deregulation of two other MYC family members, MYCN (also referred as N-Myc) and MYCL1 (also referred as L-Myc), has also been revealed in human neuroblastoma, breast cancer, lung cancer, and many other cancers." (PMID 28245597, 2017). "They found that MYC expression in MYCN amplified neuroblastoma is not generally observed, and when MYC is over-expressed it is dominant over N-MYC expression." (PMID 28587062, 2017). "The MYCN gene which is the most relevant genetic biomarker in neuroblastoma predicting poor prognosis was not amplified in this specimen." (PMID 28818093, 2017). "For MYCN, non-amplified stage 4 neuroblastoma, neurotrophic tyrosine kinase 1, or ALK paired with GFRA2, GFRA3, SSK1, GPR173, or with one another provided the most promising paired-hits." (PMID 28871274, 2017). "In order to determine if there is a correlation between MYCN and GAS5 expression levels in neuroblastoma, 15 neuroblastoma cell lines were screened (6 MYCN-amplified and 9 non-amplified) for both MYCN and GAS5 expression by qRT-PCR, normalized to GAPDH." (PMID 28035057, 2017). "While elevated MYCN levels can block the pro-apoptotic effects of RA, our results reveal that KGN can be used as a combination therapy to promote MYCN-amplified neuroblastoma cell death." (PMID 28187790, 2017). "The extent of their transcription levels can distinguish between the MYCN amplified and non-amplified neuroblastomas." (PMID 29137381, 2017). "Debatin and colleagues demonstrated that while overexpression of MYCN in neuroblastoma does not induce apoptosis, it primes the cell for cytotoxic drugs to induce apoptosis through cooperative upregulation of BAX." (PMID 26859456, 2016). "Moreover, when mRNA profiles from murine MYCN-driven neuroblastoma were included, all tumors arising in LSL-MYCN;hGFAP-Cre mice clustered together, while MYCN-induced neuroblastomas were grouped separately (PCA2)." (PMID 27769070, 2016).